CDH1 (cadherin 1)
Diseases named in the same sentence as CDH1 in open-access papers (continued):
Sharing a sentence is not in itself a finding about the gene and the disease.
invasive lobular carcinoma (continued). "An intraductal injection of lentivirus-encoding Cas9 was used to generate invasive lobular breast carcinoma (ILC) with conditional alleles of Cdh1 gene, encoding E-cadherin." (PMID 30636933, 2019). "E-cadherin (CDH1) is a master regulator of epithelial cell adherence junctions and a well-established tumor suppressor in Invasive Lobular Carcinoma (ILC)." (PMID 31444332, 2019). "Although CDH1 is key for the maintenance of epithelial stem cells, many reports reveal that CDH1 loss is associated with EMT, a cancer stem cell-like behavior, and its deficiency is characteristic of invasive breast lobular carcinomas, especially in TNBC." (PMID 28392805, 2017). "Loss of cadherin 1 (CDH1) expression, which is normally involved in cell adhesion and maintenance of tissue architecture, is a hallmark of invasive lobular carcinoma (ILCA)." (PMID 25067988, 2014). "We conducted a comparative study of CDH1-mutated and non-mutated invasive lobular carcinoma and evaluated the differences in mRNA levels, reverse-phase protein array, methylation, and miRNAs." (PMID 39201647, 2024). "In line with the current WHO guidelines, the histological diagnosis of invasive lobular carcinoma is based on H&E morphology and on the immunohistochemical characterization of E‐cadherin and the catenin complex independently from the presence of underlying CDH1 gene mutations." (PMID 38335502, 2024). "E-cadherin is negative in over 75% of invasive lobular carcinoma of the breast, as a result of mutations of the CDH1 gene." (PMID 31205468, 2019). "Invasive lobular carcinoma was also recently discovered in CDH1 germline mutation carriers who never developed HDGC." (PMID 30568591, 2018). "CDH1, the gene coding for the E-cadherin adhesion protein, is of special interest as mutations are associated with invasive lobular carcinoma, but never with ductal carcinoma." (PMID 25848941, 2015). "Hence, future studies should focus on elucidating the mechanism underlying E-cadherin inactivation via post-translational modifications in CDH1 non-mutated invasive lobular carcinoma." (PMID 39201647, 2024). "Therefore, abnormalities in E-cadherin production also exist in CDH1 non-mutated invasive lobular carcinoma." (PMID 39201647, 2024). "However, it seems that alternative mechanisms to disrupt E-cadherin function must contribute to the invasive phenotype; a fraction of patients with invasive lobular carcinoma retain E-cadherin expression and 50% of patients showing loss of E-cadherin do not have CDH1 inactivating mutations." (PMID 37795261, 2023). "Similarly, CDH1 and PIK3CA have been commonly identified in invasive lobular breast carcinoma, but whether these concurrent mutations are sensitive to PI3K/Akt/mTOR agents remains to be confirmed." (PMID 33723724, 2021). "In this study, we investigated the molecular underpinnings of E-cadherin dysregulation in invasive lobular carcinoma in the absence of CDH1 gene alterations, using comprehensive bioinformatic analyses." (PMID 39201647, 2024). "We observed that invasive lobular carcinoma cases without CDH1 alterations exhibited a significantly higher incidence of the Claudin-low subtype (p < 0.01)." (PMID 39201647, 2024). "In the best of our knowledge, only 7 previous invasive lobular carcinoma (ILC) with OGCs have been described in literature, but none of these had confirmation of the histological type by E-cadherin immunohistochemistry and/or mutational analysis of CDH1 gene nor were of pleomorphic subtype." (PMID 30153845, 2018).
hereditary diffuse gastric cancer (111 papers, 2009 to 2026). "Germline mutations in CDH1, coding for the related protein E-cadherin, are associated with a well-described cancer syndrome, including hereditary diffuse gastric cancer." (PMID 41516419, 2026). "CDH1 gene is frequently studied in the routine practice, to investigate a possible predisposition to breast and diffuse gastric cancers and to manage cancer prevention in the family." (PMID 41154377, 2025). "There are very few case reports on hereditary diffuse gastric cancer (HDGC) among Chinese individuals with CDH1 mutations." (PMID 41378303, 2025). "CDH1 mutations are also implicated in hereditary diffuse gastric cancer, predisposing some patients to both cancers." (PMID 40366456, 2025). "CDH1 dysfunction has been most significantly associated with the development of hereditary diffuse gastric cancer (HDGC), with historical estimates of cumulative incidence by 80 years of age ranging from 37-70% in men and 25-83% in women." (PMID 40551901, 2025). "Germline CDH1 pathogenic variants, associated with hereditary diffuse gastric cancer (HDGC), were more common in patients with YOGC than AOGC." (PMID 39629931, 2024). "In the case of diffuse gastric cancer, screening for mutations in the CDH1 gene is performed, while in the case of the intestinal type, there is no specific molecular background." (PMID 38867324, 2024). "Hereditary diffuse gastric cancer (HDGC) is an autosomal dominant cancer syndrome attributed to germline CDH1 mutations that carries a high risk for early onset DGC." (PMID 36869400, 2023). "We discuss the management of the risk of diffuse gastric cancer in Hereditary Lobular Breast Cancer (HLBC) through a family of 11 CDH1 carriers where foci were identified in endoscopic surveillance." (PMID 37761816, 2023). "GPVs of the CDH1 tumour suppressor gene are known to cause hereditary diffuse gastric cancer (HDGC) and hereditary lobular breast cancer (HLBC)." (PMID 37258796, 2023). "The cumulative risk by age 80 years of diffuse gastric cancer in patients with CDH1-related HDGC is approximately 70% for men and 56% for women." (PMID 36719602, 2023). "Mutational screening of the CDH1 gene is a standard treatment for patients who fulfill Hereditary Diffuse Gastric Cancer (HDGC) testing criteria." (PMID 35327954, 2022). "Hereditary diffuse gastric cancer (HDGC) is an autosomal dominant inherited cancer syndrome that has been associated with a mutation of the CDH1, and rarely the CTNNA1 gene, respectively." (PMID 35448173, 2022). "The loss of CDH1 function was traditionally implicated in the tumorigenesis of diffuse gastric cancer (DGC), and both LBC and DGC share the same histopathological characteristics, including individual or small clusters of discohesive cell growth pattern." (PMID 35686104, 2022). "Germline mutations in CDH1, the gene encoding the cell adhesion protein E-cadherin, are responsible for the cancer syndrome hereditary diffuse gastric cancer (HDGC)." (PMID 35406381, 2022). "Germline pathogenic mutations in the CDH1 gene (encoding the E‐cadherin protein) are responsible for the development of Hereditary Diffuse Gastric Cancer (HDGC; OMIM n.137215), an autosomal inherited predisposition syndrome." (PMID 35277969, 2022). "Prophylactic gastrectomy is recommended as standard of care in carriers of a pathogenic CDH1 mutation and with familial history of proven diffuse gastric cancer." (PMID 35448173, 2022). "As for Japanese, only one case of diffuse gastric cancer associated with a de novo genomic deletion of CDH1 gene has been reported so far." (PMID 33797633, 2021). "High-frequency mutations at multiple sites in CDH1 are one of the risk factors and signs of hereditary diffuse gastric cancer." (PMID 34422902, 2021).
hereditary diffuse gastric cancer (continued). "Inhibitors of sphingolipid metabolism and vesicle trafficking pathways were identified as promising candidate compounds in a cell line model of CDH1 loss, then further validated in murine-derived organoid models of hereditary diffuse gastric cancer." (PMID 35008266, 2021). "Hereditary diffuse gastric cancer (HDGC) is a rare signet-ring cell adenocarcinoma (SRCC) linked to CDH1 (E-cadherin) inactivating germline mutations, and increasingly other gene mutations." (PMID 34073553, 2021). "E-cadherin (CDH1 gene) germline mutations are associated with the development of the autosomal cancer syndrome known as hereditary diffuse gastric cancer." (PMID 33809393, 2021). "Hereditary diffuse gastric cancer (HDGC) is an inherited cancer syndrome associated with CDH1 germline mutations." (PMID 34503169, 2021). "For example, CDH1 germline mutations are closely related to the occurrence of hereditary diffuse gastric cancer." (PMID 34422902, 2021). "In this study, we describe an extended family pedigree harboring a CDH1 missense variant that strongly segregates with diffuse gastric cancer." (PMID 34503169, 2021). "Germline CDH1 Pathogenic (P) and Likely Pathogenic (LP) variants are actionable variants in Hereditary Diffuse Gastric Cancer (HDGC), predisposing for diffuse gastric cancer (DGC) and lobular breast cancer (LBC)." (PMID 33530161, 2021). "The CDH1 mutation is the only germline molecular mutation related to hereditary diffuse gastric cancer and lobular breast cancer." (PMID 34422902, 2021). "In this study, we describe the identification of the novel CDH1 G212E variant in a large family strongly affected by diffuse gastric cancer." (PMID 34503169, 2021). "The present study addressed the significance of a novel CDH1 variant, G212E, identified in an unusually large pedigree displaying strong aggregation of diffuse gastric cancer." (PMID 34503169, 2021). "The studies found suggested that a CDH1 mutation carrier has an increased risk of developing diffuse gastric cancer and invasive lobular breast cancer in his/her life." (PMID 33062523, 2020). "In 1998 pathogenic germline variants (PV) in the CDH1 gene responsible for multiple, early-onset diffuse gastric cancer in three Maori kindreds were identified." (PMID 33322525, 2020). "The establishment of this association between CDH1 and hereditary diffuse gastric cancer (HDGC) was a breakthrough which was needed for early identification of this genetic mutation in early prevention and management." (PMID 33062523, 2020). "The systematic review conducted for HDGC syndrome established the relationship between the CDH1 mutations and diffuse gastric cancer." (PMID 33062523, 2020). "In general, germline CDH1 mutations were identified in subjects with a strong family history of diffuse gastric cancer or lobular breast cancer." (PMID 30895400, 2019). "Male and female CDH1 mutation carriers have a 70% (95% CI 59–80%) and 56% (95% CI 44–69%) cumulative lifetime risk of developing diffuse gastric cancer, respectively." (PMID 30895400, 2019). "Germline pathogenic variants in the CDH1 gene are a well-established cause of hereditary diffuse gastric cancer (HDGC) syndrome." (PMID 31600923, 2019). "Our results demonstrate that germline CDH1 mutations are a significant contributor to the high frequency of diffuse gastric cancer in New Zealand Māori." (PMID 29589180, 2019). "In Family A, the large Māori kindred in which the first pathogenic CDH1 mutation was identified, the overall penetrance of diffuse gastric cancer is approximately 70%." (PMID 29589180, 2019). "Pathogenic germline CDH1 mutations are causative of hereditary diffuse gastric cancer, a cancer predisposition syndrome primarily characterised by an extreme lifetime risk of developing diffuse gastric cancer." (PMID 29589180, 2019). "These leads represent molecularly selected treatment options tailored to the treatment of CDH1-deficient familial gastric cancer." (PMID 29468433, 2018).
hereditary diffuse gastric cancer (continued). "Hereditary diffuse gastric cancer is a cancer predisposition syndrome associated with germline mutations of the E-cadherin gene (CDH1; NM_004360)." (PMID 29468433, 2018). "Hereditary diffuse gastric cancer due to CDH1 germline mutations has to date largely escaped the benefits of the personalized medicine approach." (PMID 28460635, 2017). "Hereditary diffuse gastric cancer (HDGC) is an autosomal dominant cancer susceptibility syndrome due to germline mutations within the E-cadherin (CDH1) gene locus cadherin (CDH1; NM_004360)." (PMID 28460635, 2017). "Germline mutations and polymorphisms detected in CDH1 exonsin hereditary diffuse gastric cancer in Brazil." (PMID 27192129, 2016). "The reported penetrance of germline CDH1 mutations is high in families with hereditary diffuse gastric cancer (HDGC)." (PMID 27064202, 2016). "The CDH1 mutation was previously reported in a family with three affected members with diffuse gastric cancer." (PMID 24373500, 2013). "E-cadherin gene (CDH1) mutations were identified as the causal event underlying the hereditary diffuse gastric cancer (HDGC) syndrome." (PMID 23484115, 2013). "Predisposing CDH1 mutations have been encountered in about 30% of strictly selected Hereditary Diffuse Gastric Cancer (HDGC) families." (PMID 23231819, 2012). "Germline mutations of the CDH1 gene result in loss of function of E-cadherin gene in approximately one third of the cases of Hereditary Diffuse Gastric Cancer (HDGC)." (PMID 21853084, 2011). "Germline CDH1 mutations were first described in three New Zealand families with early-onset, poorly differentiated, high-grade, diffuse gastric cancer." (PMID 19888225, 2010). "Hereditary diffuse gastric cancer (HDGC) is an autosomal dominant cancer caused by CDH1 mutation." (PMID 39895902, 2025). "Younger people may be more likely to have cancer associated with genetic factors, such as hereditary cancer syndromes such as Lynch syndrome or CDH1 mutations associated with hereditary diffuse gastric cancer." (PMID 39451226, 2024). "Hereditary diffuse gastric cancer (HDGC) is a cancer syndrome caused by inactivating germline mutations in CDH1, but its mechanism remains unclear." (PMID 37305583, 2023). "The results support a hereditary diffuse gastric cancer associated with this CDH1 variant." (PMID 37393258, 2023). "Specific inherited GC syndromes, such as hereditary diffuse gastric cancer (HDGC) caused by inactivating mutations in the tumor suppressor gene CDH1, may also lead to a higher risk of GC." (PMID 37174105, 2023). "The three primary familial gastric cancers include hereditary diffuse gastric cancer, familial intestinal gastric cancer and gastric adenocarcinoma and proximal polyposis of the stomach, caused by germline mutations in genes such as CDH1, CTNNA1 and APC." (PMID 34359744, 2021). "Among them, CDH1 germline mutation is the main cause of diffuse gastric cancer." (PMID 34422902, 2021). "However, substantial evidences have demonstrated an increased risk for LBC among CDH1 mutations carriers regarding their familial history for diffuse gastric cancer (DGC)." (PMID 33827469, 2021). "CDH1 gene mutation or transcription silencing is related to familial diffuse gastric cancer." (PMID 34422902, 2021). "Up to 70% of sporadic diffuse gastric cancers (SDGCs) harbor somatic mutations in CDH1." (PMID 34576114, 2021). "However, genetics (e.g., CDH1 germline mutations) and female sex are important in diffuse gastric cancer." (PMID 32899442, 2020). "Not all families fulfilling these criteria have disease causing variants in CDH1, indicating that other genes might also be involved in predisposition for diffuse gastric cancer." (PMID 32518610, 2020). "In addition, germline mutations in CDH1 predispose to the autosomal dominant cancer syndrome Hereditary Diffuse Gastric Cancer (HDGC)." (PMID 31467357, 2019).
hereditary diffuse gastric cancer (continued). "In addition, germline CDH1 mutations genetically characterise the inherited cancer syndrome Hereditary Diffuse Gastric Cancer (HDGC)." (PMID 30066183, 2019). "Hereditary Diffuse Gastric Cancer (HDGC) is characterized by multiple foci of stage T1a signet ring cell carcinoma that develop in the stomachs of CDH1 mutation carriers following the downregulation of the 2nd CDH1 allele." (PMID 31467357, 2019). "CDH1—Germline alterantions of the tumor suppressor gene (E-cadherin) are associated with hereditary diffuse gastric cancer (HDGC) and occur in approximately 40% of HDGC families." (PMID 39335135, 2024). "This cohort study uses whole-exome and targeted sequencing to assess the incidence rate of CDH1 germline alterations in hereditary diffuse gastric cancer, provide a genetic landscape for the disease, and identify new susceptibility genes among Chinese patients with hereditary diffuse gastric cancer." (PMID 36484990, 2022). "Hereditary diffuse gastric cancer (HDGC) is a complex and multifactorial inherited cancer predisposition syndrome caused by CDH1 germline mutations." (PMID 33809393, 2021). "Hereditary Diffuse Gastric Cancer (HDGC) is a complex inherited syndrome caused by CDH1 germline mutations." (PMID 34066044, 2021). "Hereditary diffuse gastric cancer (HDGC) is a diffuse-type autosomal dominant familial syndrome caused by a germline mutation in the cadherin-1 gene (CDH1)." (PMID 33941229, 2021). "Germline pathogenic variants in the cadherin-1 (CDH1) gene cause a predisposition to hereditary diffuse gastric cancer (HDGC)." (PMID 33941229, 2021). "Therefore, prophylactic total gastrectomy may be the most desirable option for individuals with CDH1 mutations and a family history of diffuse gastric cancer." (PMID 34422902, 2021). "The germline mutation of CDH1 is inherited by autosomal dominant manner and develops Hereditary Diffuse Gastric Cancer (HDGC)." (PMID 33797633, 2021). "While CDH1 germline alterations are known to cause specific types of epithelial cancer, e.g. diffuse gastric cancer and invasive lobular breast cancer, our data newly add certain neuroepithelial and epithelial brain tumors to the phenotype spectrum caused by rare CDH1 variants." (PMID 33929593, 2021). "However, the contribution CDH1 mutations make to the high incidence of diffuse gastric cancer in Māori is unknown." (PMID 29589180, 2019). "As the most comprehensive study of germline CDH1 mutations in a specific ethnic group, our study demonstrates the significant impact pathogenic CDH1 mutations have on the high frequency of early-onset diffuse gastric cancer cases in the New Zealand Māori population." (PMID 29589180, 2019). "Patients with hereditary diffuse gastric cancer (HDGC), a cancer predisposition syndrome associated with germline mutations of the CDH1 (E-cadherin) gene, have few effective treatment options." (PMID 28460635, 2017). "Hereditary diffuse gastric cancer (HDGC) is a hereditary autosomal inherited syndrome associated with CDH1 germline mutations." (PMID 25180051, 2014). "CDH13 is interesting also in the context that another gene in the same family, CDH1, is responsible for familial early onset diffuse gastric cancer." (PMID 39543761, 2024). "Hereditary diffuse gastric cancer is autosomal dominant that alters the E-cadherin genes (CDH1) and beta-catenin (CTNNA1)." (PMID 39335195, 2024). "Familial diffuse gastric cancer and hereditary diffuse gastric cancer are the most recognizable, familial gastric cancer caused by APC, CDH1, and CTNNA1 gene mutations, respectively." (PMID 38649672, 2024). "A deleterious CTNNA1 germline variant was found in 0.7% (1/141) of diffuse gastric cancer patients meeting the 2020 IGCLC criteria, as compared to the rate of 2.8% of CDH1 deleterious variants found by us in this setting." (PMID 37686589, 2023). "In those with CDH1 GPV with a personal or familial history of diffuse gastric cancer, this is recategorized as HDGC." (PMID 37258796, 2023).